EGFR (epidermal growth factor receptor)
Diseases named in the same sentence as EGFR in open-access papers (continued):
Sharing a sentence is not in itself a finding about the gene and the disease.
tumor (continued). "Indeed, EGFR expression was significantly up-regulated in patient #8 tumour versus adjacent brain tissue (p < 0.0001, t-test)." (PMID 27843499, 2016). "Strategies have been proposed to overcome anti-EGFR resistance resulting from tumor heterogeneity." (PMID 27699178, 2016). "Plasma c-Met levels < 766 ng/ml before EGFR-TKI treatment were associated with a negative c-Met status of the resistant tumor in 34 of 37 patients (91.9%, P= 0.051)." (PMID 27213587, 2016). "We also investigated the immediate changes to EGFR signaling and the tumor immune microenvironment." (PMID 27494838, 2016). "The expression level of CAR10, EGFR, and YB-1 was tested in the tumor tissues by qRT-PCR or Western blot, and the results showed that in the lungs of the mice inoculated with shCAR10-A549-luciferase cells, the expression of CAR10, EGFR and YB-1 was markedly lower than the control group." (PMID 27322209, 2016). "Since our results showed that P19 and P26 not only bind to panitumumab, but also attenuate the binding of panitumumab to EGFR, we investigated whether P19 and P26 could prevent panitumumab from inhibiting tumor cell growth." (PMID 27659529, 2016). "The tumor heterogeneity captured by ctDNA NGS analysis was stronger for EGFR wild-type tumors and may reflect tobacco or chemotherapy-induced molecular heterogeneity." (PMID 28027313, 2016). "Our results strongly suggest that the IL-1 pathway may serve as a novel mechanism responsible for tumor resistance to EGFR TKIs in HNSCC therapy." (PMID 27738319, 2016). "Multicenter academic prospective phase II study with erlotinib in patients with an activating EGFR tyrosine kinase (TK) domain somatic mutation (any exon encoding the kinase domain) in the tumor and no prior treatment for their advanced disease." (PMID 27032107, 2016). "Finally, using a genetically modified sub-line of NCI-H1975 cells, we conducted in vivo experiments and imaged EGFR activity in real-time using a non-invasive bioluminescence reporter and also assessed the effect of treatment on tumor growth." (PMID 27612423, 2016). "Notably, we provide evidence that patients who experience more profound and longer responses to EGFR blockade preferentially develop EGFR ECD mutations, while RAS mutations emerge more frequently in patients with limited tumour shrinkage and shorter PFS." (PMID 27929064, 2016). "For example, EGFR could suppress the maturation of specific tumor-suppressor miRNAs in response to hypoxic stress through phosphorylation of argonaute 2 (AGO2)." (PMID 26646588, 2016). "Therefore, scoring system 1 for EGFR expression seems to be more valuable for predicting tumor aggressiveness and prognosis." (PMID 25953424, 2015). "In this study, we found that HER-3 expression on tumor cells was increased after EGFR inhibition." (PMID 26538233, 2015). "In the context here discussed, a tumor cell is deemed resistant when it “shortcuts”, “compensates for” or “bypasses” receptor inhibition by establishing robust activation of survival pathways downstream of the EGFR or through other RTK signaling activation." (PMID 25885672, 2015). "Furthermore, both xenografts of EGFR-TKI-sensitive (PC-9) and EGFR-TKI-resistant (RPC-9) cell lines showed similar anti-tumor effects in response to TAE226 in vivo." (PMID 26090892, 2015). "From day 14 and onwards, the tumor volume in the Pan-HER group was significantly smaller (p < 0.05) than that of the control group or any of the groups receiving antibody mixtures targeting EGFR, HER2 or HER3 individually." (PMID 26460961, 2015). "Here we investigated whether expression of intrinsic mPGES-1 in advanced PCa cells enhanced their aggressiveness and might be critical for EGFR-mediated tumour progression." (PMID 26113609, 2015).
tumor (continued). "Western blot analysis of tumor samples from mice sacrificed on day 14, after 1 week of treatment, demonstrated that cetuximab plus saracatinib efficiently interferes with EGFR-dependent signal transduction by reducing phosphorylation/activation of EGFR, Src, Akt and MAPK." (PMID 26325669, 2015). "Whereas the reason for poor inhibition to FAK or IGF-IR activity in NSCLC is not clear, our findings indicated that TAE226 strongly inhibited the mutant EGFR, compared to FAK and IGF-IR, in cells that are “addicted” to the mutant EGFR, resulting in the anti-tumor activity of TAE226." (PMID 26090892, 2015). "In patients with concurrent EGFR mutation and ALK rearrangement, the tumor response to certain TKIs may be inferior to historical data, depending on which genetic alteration is the major oncogenic driver." (PMID 26268359, 2015). "As discussed, depending on the assay type, reliable EGFR mutational analysis requires significant numbers of tumor cells and frequently macrodissection to generate sufficient tumor DNA and avoid false negative test results." (PMID 26317646, 2015). "Therefore, patients with these EGFR gene TKI-sensitive mutations have a significantly better response to EGFR-TKIs, whereas those with wild-type EGFR genes exhibit a worse tumor response." (PMID 26047516, 2015). "Moreover, we pre-treated GB30 and U251 cells with EGFR neutralizing antibody (the same clone as the scFv origin), followed by co-culture of the pre-treated tumor cells with mock-transduced NK-92 cells or NK-92-EGFR-CAR cells." (PMID 26155832, 2015). "Generally, EGFR is highly expressed in tissues of gastric, esophageal and hepatic tumors, whereas it is barely expressed in corresponding normal tissues, suggesting that overexpression of EGFR may be related with tumor onset and progression." (PMID 26648997, 2015). "The reason for these results may be that most of the tumor cells were wild-type KRAS subclones that could respond to anti-EGFR antibody treatment in the early stages of treatment." (PMID 26701781, 2015). "Since the EGFr signaling pathway involves multiple downstream phosphorylation reactions and crosstalk with other signaling pathways, it is possible that the anti-tumor effects of EGFr inhibition can be enhanced by inhibiting other downstream effectors of EGFr signaling." (PMID 26458879, 2015). "Integrating this knowledge into the EGFR paradigm, it is plausible that, if accurately detected, phosphorylated EGFR (pEGFR) may indeed reflect receptor utilization by the specific tumour." (PMID 26149458, 2015). "One of the responses was long lasting, and the tumor harbored an EGFR exon 19 deletion." (PMID 26325669, 2015). "Another way Celecoxib could alter Cetuximab efficacy is through the increased expression of EGFR on colon TAFs: in vivo, tumor stroma wrapping epithelial cancer cells could sequester and lower the levels of drug available for cancer targeting." (PMID 25987127, 2015). "The results of the present study suggest that targeting EGFR may suppress HIF-1α-mediated tumor angiogenesis." (PMID 25997612, 2015). "For example, treatment of ectopic mammary fat pad tumours in mice with a combination of chemotherapy, and PARP inhibitor and EGFR-targeted radioimmunotherapy was significantly more effective in preventing and even reversing tumour growth than single or double agent treatments." (PMID 25969993, 2015). "However, we also believe there are cases where new biopsies are likely needed to accurately assess the mutational landscape of a tumor and design appropriate therapy, for example, in CRC patients who progress after certain therapy (i.e. anti EGFR therapy)." (PMID 25974029, 2015). "ADAM12 is selectively expressed in GBM tissues where it might be involved in supporting tumor cell proliferation that is mainly sustained by enhanced EGF signaling through EGFR." (PMID 26437223, 2015).
tumor (continued). "Dual-specific HER2 and EGFR inhibitors like lapatinib may be more effective than single agents in such cases, but may require analysis of multiple tumor areas." (PMID 25649416, 2015). "Moreover, recently it has been demonstrated that the scaffolding protein NHERF1 sensitizes EGFR-dependent tumor growth, motility, and invadopodia function to anti-EGFR (gefitinib) treatment in TNBC cells." (PMID 26258011, 2015). "Moreover, monoclonal antibodies to either SPINK1 or EGFR (cetuximab) significantly slowed down tumor growth in SPINK1‐positive tumor xenografted mice." (PMID 25809148, 2015). "We now show that intracellular sodium regulates trafficking of the EGFR receptor and we suggest that changes in the intracellular sodium level in tumor cells may contribute to therapeutic resistance to therapeutic anti-EGFR antibodies." (PMID 26382850, 2015). "Western blot analysis of tumor lysates indicated approximately 30% lower levels of EGFR in NCI-H3255 tumors compared to HCC827, consistent with the approximately 30% lower SUV of [11C]erlotinib in NCI-H3255 tumors at 12 min after injection, the time of peak radioactivity uptake in these tumors." (PMID 25853010, 2015). "Moreover, tumor-suppressive miR-23b and miR-27b directly regulated tyrosine kinase receptor genes EGFR and c-Met." (PMID 25405368, 2015). "Palliative therapy, including chemotherapy, which is usually platinum based, and traditional anti-tumor monoclonal antibodies (mAbs, e.g. cetuximab) function by targeting molecules on the tumor cell surface (e.g. EGFR), resulting in functional receptor blockade and inhibition of signal transduction." (PMID 26562534, 2015). "However, the connection between the GAS5 levels and the sensitivity to EGFR-TKIs in tumor cells is unclear and remains to be elucidated." (PMID 25925741, 2015). "Low levels of Cbl and high expression of EGFR in the peritumoral liver tissue, but not in tumor tissue, was significantly associated with high incidence of recurrence and poor overall survival of HCC after curative resection." (PMID 26474280, 2015). "This indicates an attractive new avenue of combination approaches for cancer therapy that may enhance the potency of EGFR inhibitory agents on tumours." (PMID 26497899, 2015). "Therefore, therapeutically targeting COX-2 and fibronectin in EGFR-stimulated HNSCC metastasis would be of interest because metastasis represents the main clinical challenge after primary tumor resection." (PMID 25595899, 2015). "As MPM tumors are known to frequently exhibit a hypoxic phenotype and often express high levels of EGFR, this may explain, at least in part, the reduced levels of mature miR-193a-3p we observe in our tumor series." (PMID 26125439, 2015). "Thus, KRAS mutations apparently have a low or no selective advantage unless they are acquired early during carcinogenesis or the tumour is treated with EGFR-targeted agents." (PMID 25555261, 2015). "However, the first-generation EGFR tyrosine-kinase inhibitors (TKIs) gefitinib and erlotinib show minimal tumor inhibition efficacy as monotherapies in HNSCC." (PMID 25595899, 2015). "PD-1 positive tumor infiltrating lymphocytes and PD-L1 expressing tumor cells were seen in 18 of 42 cases (43%) of which 8 cases lacked other biologic targets including EGFR mutations, HER2, cMET, ALK, or ROS1 rearrangements." (PMID 25941796, 2015). "Such a difference in FaDu tumor response to panitumumab and cetuximab may be due to the difference in the binding characteristics of these therapeutic antibodies to EGFR." (PMID 25355701, 2015). "EGFR amplification was exclusively found in tumors with wild-type IDH1/2 (p < 0.0001) and showed co-occurring association with TERTp mutation in IDH1/2 wild-type tumor subset (p = 0.002)." (PMID 26369702, 2015). "Similarly, afatinib (BIBW2992) is another irreversible pan-EGFR inhibitor that has been shown to be effective in inhibiting the tumor growth of lung and breast cancer, both in vitro and in vivo." (PMID 25686822, 2015).
tumor (continued). "Interestingly, a recent study has shown that in human HCC and in mouse HCC models the EGFR is upregulated in liver macrophages where it plays a tumor-promoting function." (PMID 26729094, 2015). "Here, using digital PCR assay as an alternative and noninvasive method, we examined plasma and tumor samples from patients with relapsed NSCLC to establish the inter-relationships existing among T790M mutation, activating EGFR mutations, HER2 amplification, and MET amplification." (PMID 26334838, 2015). "A possible advantage of combining tumor suppressor gene therapy with small molecule targeted therapy, such as erlotinib, is enhancement of sensitivity that may extend over wild type EGFR cell types with differing mechanisms of drug resistance." (PMID 26053020, 2015). "From these observations we suggest that energy level could be the limiting factor for the tumor cells survival in the presence of EGFR inhibitors." (PMID 25948104, 2015). "Primary tumors co-injected with MSCs expressed higher phospho-epidermal growth factor receptor (p-EGFR) and promoted metastasis development after tumor resection, effects that were abrogated by treatment with the epidermal growth factor receptor (EGFR) inhibitor, erlotinib." (PMID 25887413, 2015). "In this study, we used RNA as a template in order to enrich mutant EGFR from tumor cells." (PMID 26436086, 2015). "To see whether EGFR expression in the same tissue microarray is correlated with KLF8 expression and the tumor invasive potential, we performed an immunohistochemical (IHC) staining for EGFR expression." (PMID 26025929, 2015). "This suggests that the modest drug-induced increase in stability of the EGFR homodimer may have a significant biological impact on the tumor cell’s proliferation potential." (PMID 25762314, 2015). "Hitherto, elevated tumor uptake of [11C]erlotinib has been demonstrated only in tumors harboring EGFR exon 19 deletions compared to tumors without activating EGFR mutations." (PMID 25853010, 2015). "Moreover, the combination of PARP inhibition with an upstream blocker of pro-survival signalling pathways arising from the EGFR, the EGFR inhibitor erlotinib, induced a dramatic reduction in tumour growth in an orthotopic mouse model." (PMID 25576921, 2015). "Genetic analysis of NSCLC revealed that the EGFR and its downstream targets, the members of the mitogenic RAS/RAF/MEK/ERK signalling cascade, are frequently mutated or overexpressed in NSCLC types of tumours." (PMID 25674792, 2015). "Firstly, using cell invasion-related molecules, including matrix metalloproteinase-9 and urokinase-type plasminogen, EGFR tyrosine kinase inhibitors may act directly on tumor cells." (PMID 25663922, 2015). "Tumor cells overexpressing EGFR are common, allowing for selective binding of nimotuzumab." (PMID 25185971, 2015). "In addition, the Rho–ROCK pathway also promotes EGFR–Ras–extracellular-signal-regulated kinase pathway-mediated tumor cell proliferation, and activated EGFR promotes cancer cells to resist apoptosis by activating phosphatidylinositol 3-kinase–Akt pathways." (PMID 26344692, 2015). "Based upon this theory a treatment break after developing acquired anti-EGFR resistance may allow the dominant clone that is KRAS-wt to repopulate and render a tumor sensitive to anti-EGFR therapy." (PMID 26474549, 2015). "In addition, aCGH showed amplification of chromosome 7p, containing EGFR with a log2 ratio of 0.399, or a 1.32-fold change in tumor DNA relative to germline DNA." (PMID 25962155, 2015). "We hypothesize that tumor maturation and keratinization contributes to decreased ligand affinity of EGFR or tissue penetration of the antibody, and may promote EGFR-inhibitor resistance." (PMID 26120042, 2015).
tumor (continued). "Although the basis for this paradoxical response of EGFR to Gefitinib is unclear, both inhibitors caused reduction of AKT phosphorylation, indicating that the ErbB pathway is responsible for the persistent activation of AKT in Smarcb1 deficient tumor cells." (PMID 26370283, 2015). "Researchers has identified that overexpression of EGFR could increase the proliferation of tumor cell through the PI3K-AKT signaling pathway and it is likely to be an independent predictor of poor prognosis." (PMID 26538117, 2015). "No other significant associations between p-EGFR tumor or stroma intensity and receptor status were observed in either the full cohort or the IBC/non-IBC subsets." (PMID 25887413, 2015). "We modeled mixed effects in the setting of multiple simultaneous tumors, and identified EGFR as a clinical target activated by tumor stromal cells that limits the growth of highly proliferating, metastatic, E-cadherin-positive cells in this IBC xenograft model." (PMID 25887413, 2015). "The ability to detect phosphorylated EGFR in tumor cells, especially in tumor circulating cells, may provide an additional insight into the biology of cells with greater metastatic potential." (PMID 25523156, 2015). "EGF contributed to tumor proliferation in EC cell lines along with EGFR expression in vitro." (PMID 26673416, 2015). "Activation of EGFR pathways is critical in driving tumor invasion." (PMID 25797258, 2015). "AREG is one of essential miR-34a targets, over-expression of which could rescue miR-34a mediated tumor invasion defects and EGFR inhibition." (PMID 25762634, 2015). "However, it is extremely interesting that the Ad-GSC subpopulation and Ad-GSC tumor xenografts express relatively low EGFR levels providing additional evidence that Ad-GSCs are a distinct GSC population." (PMID 25955030, 2015). "Thus, these liquid specimens can complement with tumor tissues and help to guide EGFR-TKI therapy in NSCLC." (PMID 26227959, 2015). "Subsequently, the blockage of EGFR by h-R3 reduces the activation of Akt and result in tumor death." (PMID 26124180, 2015). "Some data suggest that the relatively inferior response to second-line EGFR-TKIs may result from the decreased abundance of EGFR-mutant tumor cells after chemotherapy." (PMID 25552401, 2015). "Molecular interactions are both intracellular and extracellular, and so it is a reasonable assumption that the internalisation and cytoplasmic accumulation of EGFR may indeed alter tumour cell morphology, metabolism and confer an invasive cellular phenotype." (PMID 26149458, 2015). "Here we investigated whether expression of intrinsic microsomal PGE synthase-1 (mPGES-1) enhanced aggressiveness of PCa cells and might be critical for epidermal growth factor receptor (EGFR)-mediated tumour progression." (PMID 26113609, 2015). "Almost tumor samples expressing MET are also positive for EGFR expression." (PMID 26215852, 2015). "In our study, erlotinib patients were included without knowledge of the EGFR mutation status in tumour tissue." (PMID 25743274, 2015). "Up-regulated EGFR signaling is known to initiate a cascade of events and lead to cell proliferation, migration, invasion and inhibition of apoptosis, all of which promotes tumor progression." (PMID 26250800, 2015). "It is possible that other signalling pathways (i.e. RAS, EGFR, Notch) may also be involved in Cul4A-mediated tumour growth." (PMID 26218750, 2015). "Over expression of DCBLD223 may act as an oncogene interacting with the EGFR and PI3K/Akt signaling pathways; gain of function of DCBLD2 mutation (Indel) could participate with cellular proliferative pathways to promote tumor progression." (PMID 26619400, 2015). "The persistent phosphorylation of HER2 and EGFR at these lower drug concentrations in tumor may be mediated through increased expression of p-HER3 leading to the formation of heterodimers that are resistant to inhibition by lapatinib." (PMID 26571496, 2015).